NOTCH3 (notch receptor 3)
Diseases named in the same sentence as NOTCH3 in open-access papers (continued):
Sharing a sentence is not in itself a finding about the gene and the disease.
tumor (continued). "It is worth noting that the tumor size was much smaller when EGCG was injected into nude mice inoculated with Lv-V7 OSCs in combination of Notch3 knockdown lentivirus (Lv-Notch3-)." (PMID 29475441, 2018). "Notch2 or Notch3 signaling have been shown to suppress tumor growth through a reduction of stem cell number, and to inhibit the tumorigenesis and metastasis of breast cancers." (PMID 30100605, 2018). "As expected, higher Notch3 levels were observed in tumor tissues and NSCLC cells compared to normal lung tissue and normal cells, respectively." (PMID 29765324, 2018). "Notch3/4 were shown to have increased expression in low-burden metastatic cells relative to the primary tumor." (PMID 30515368, 2018). "Blocking this signalling pathway with MRK-003, a γ-secretase inhibitor, downregulated Notch3 signalling, restrained cancer cell growth, and promoted tumour cell apoptosis in vitro and in vivo." (PMID 30470250, 2018). "Among the Notch receptors, Notch-3 and Notch-4 seem to have eminent role in normal breast growth, even though Notch-4 demonstrates increased activity (upregulation) in the neoplastic tumor vasculature." (PMID 30111989, 2018). "In hepatocellular cancer, both Notch1 and Notch3 levels correlated with tumor grade, invasion, and metastasis." (PMID 29462871, 2018). "By combining the three tumors with NOTCH2 locus amplification and a tumor with NOTCH3 locus amplifications, seven tumors with an activated NOTCH pathway were identified out of 84 tumors." (PMID 28636652, 2017). "Whereas Notch3 is normally expressed in smooth-muscle cells surrounding large vessels, we observed that Notch3 was upregulated in tumour endothelial cells." (PMID 28719575, 2017). "The LLC1 model thus provides a good model to study the functional impact of Notch3 aberrant expression on tumour vasculature." (PMID 28719575, 2017). "The differing changes in expression of BCRP and NOTCH3 emphasize the importance of tumor profiling and precision oncology in therapeutic strategies for PDAC, and the need to target nodal proteins like APE1 that can affect multiple pathways." (PMID 28922540, 2017). "While analysing the importance of Notch3 in the stroma during tumour progression, we observed an unexpected pro-apoptotic activity of Notch3." (PMID 28719575, 2017). "We next assessed the role of this aberrant expression of Notch3 in tumour vasculature by establishing a model in which Notch3 is silenced only in the stroma but not in the tumour cells." (PMID 28719575, 2017). "We propose here that Notch3 by acting as a dependence receptor in endothelial cells regulate tumour angiogenesis by regulating endothelial cell death." (PMID 28719575, 2017). "Along this line, using Notch3 mutant mice, we demonstrate that tumour growth and angiogenesis are increased when Notch3 is silenced in the stroma." (PMID 28719575, 2017). "Notch1, Notch2 and Notch4 mRNA expression levels were similar in AtT20 cells and normal adult pituitaries whereas Notch3 mRNA expression was reduced in corticotrope tumor cells in relation to normal mouse pituitary cells." (PMID 28915655, 2017). "Here the authors report a pro-apoptotic function of Notch3 in endothelial cells; consequently, when Notch3 is silenced in stroma cells, tumour growth and angiogenesis are increased." (PMID 28719575, 2017). "It seems, therefore, that the tumour suppressive capacity of miR-206 can be explained by both direct Notch3 signaling inhibition and indirect cross-talk with other signaling pathways involving CDH2 and MMP-9." (PMID 29104587, 2017). "Notch3 signaling is activated by the canonical Wnt/β-catenin pathway and results in altered proliferation and apoptosis of tumor cells." (PMID 28416766, 2017). "Here we describe an unexpected pro-apoptotic role of Notch3 in regulating tumour angiogenesis independently of the Notch canonical pathway." (PMID 28719575, 2017).
tumor (continued). "This function of Notch3 appears in a context in which Notch3 is aberrantly expressed in the pathological tumour vascularization where Notch3 limits tumour angiogenesis through an unexpected pro-apoptotic activity." (PMID 28719575, 2017). "This prompted us to investigate a possible role of this aberrant expression of Notch3 in tumour endothelial cells." (PMID 28719575, 2017). "Notch3 protein levels were significantly higher in urothelial cancer tissues compared to non-tumor tissues (P < 0.05)." (PMID 28416766, 2017). "In this region Notch1 and Notch3 was also ectopically expressed, appearing diffusely in the tumor epithelium." (PMID 28086833, 2017). "Further confirming the role of Notch3 in DAPT-induced cell death, we also showed that tumour-associated endothelial cells of tumours purified from Notch3LacZ/LacZ;KrasG12D/+ mice were not sensitive to DAPT treatment." (PMID 28719575, 2017). "Notch3 knockdown resulted in decreased proliferation of urothelial cancer cells in vitro and decreased xenograft tumor growth in vivo." (PMID 28416766, 2017). "The results showed that Notch3 was expressed in adjacent non-tumor tissue but that its expression was much higher in tumor tissues." (PMID 28416766, 2017). "The Notch3 ligand Jagged-1 is upregulated in a fraction of human cancer and our data support the view that Jagged-1, produced by cancer cells, is inhibiting the apoptosis induced by the aberrant Notch3 expression in tumour vasculature." (PMID 28719575, 2017). "This indicates that the apoptotic pathway mediated by Notch3 accounts, at least in part, for the regression of the tumour vasculature following DAPT treatment." (PMID 28719575, 2017). "Based on the combined data, we assume that CAFs in OSCCs ‘mimic’ the function of mural cells through induction of NOTCH3, which leads to the promotion of tumor angiogenesis." (PMID 27124156, 2016). "Employment of a similar molecular targeted drug against the Notch signaling pathway in OSCC treatment will be useful for blocking excessive NOTCH3 activity in CAFs, which would suppress tumor angiogenesis." (PMID 27124156, 2016). "Immunohistochemical study of 93 human tongue OSCC cases indicated that about one third of OSCCs showed NOTCH3 expression in CAFs, and that this expression significantly correlated with tumor-size." (PMID 27124156, 2016). "In HeLa and C2C12 cells, miR-206 targets NOTCH3 expression to induce cell-cycle arrest and the inhibition of tumor cell migration." (PMID 27103465, 2016). "The AMOP domain had an important role in MUC4/Y (MUC4)-mediated tumour angiogenesis and metastasis of PC cells; and the NOTCH3 signaling was involved." (PMID 27287498, 2016). "By meta-analysis, NOTCH1 and NOTCH3 were correlated with tumor progression and poor prognosis in NSCLC." (PMID 27938406, 2016). "In agreement with the observation obtained at the mRNA level, immunostaining for the Notch3 protein further demonstrated an increased number of Notch3+ cells in the tumor tissue." (PMID 27378829, 2016). "Notch3 is known to play a tumor suppressive role in medullary thyroid carcinoma, but the role of Notch signaling in other NETs is understudied." (PMID 27148486, 2016). "Pathologically, Notch3 expresses in cancer cells of various origins, including breast, ovary and colon, and plays a role in the regulation of tumor progression." (PMID 27102435, 2016). "Notch3 expression is decreased in SCLC compared to non-tumor lung tissue by immunohistochemistry, suggesting that Notch3 is involved in tumor suppression in SCLC." (PMID 27148486, 2016). "To investigate the distribution of NOTCH3 expressing cells in the tumor microenvironment, we immunohistochemically examined NOTCH3 expression in surgical specimens from 93 cases of tongue OSCC." (PMID 27124156, 2016). "It is conceivable that both the tumor-suppressive and the oncogenic properties of Notch3 take place at the same time, and the outcome relies upon the cellular context." (PMID 28036048, 2016).
tumor (continued). "Overexpression of Notch1 and Notch3 has been associated with increased risk of lymph node metastasis and advanced TNM (tumor size, lymph nodes, and metastases) stages." (PMID 27847554, 2016). "The immunohistochemical study using human OSCC samples indicated that NOTCH3 expression in CAFs significantly correlated with T-stage (tumor size)." (PMID 27124156, 2016). "Another Notch family receptor, Notch3, displayed significant positive Spearman correlation with PlexinD1 in different tumor types." (PMID 27749937, 2016). "In this study, we demonstrated that OSCCs stimulated the surrounding CAFs to express NOTCH3 in a cell-to-cell contact dependent manner, which activated the CAFs and resulted in their involvement in angiogenesis, thereby promoting tumor growth." (PMID 27124156, 2016). "Micro-vessel density at the tumor invasive area was significantly increased in the NOTCH3(+)CAFs group compared to the NOTCH3(-)CAFs group." (PMID 27124156, 2016). "In conclusion, the present study provides evidence that AMOP domain plays the key role in MUC4/Y(MUC4)-mediated tumour angiogenesis and metastasis of PC cells partly through the NOTCH3 signalling and its downstream target genes: VEGF-A, MMP-9 and ANG-2." (PMID 27287498, 2016). "Fibroblasts in cancer stroma, especially those adjacent to the tumor periphery, showed positive staining for NOTCH3 (31 out of 93 cases, 33.3%)." (PMID 27124156, 2016). "These authors showed a reduced expression of Nocth1 correlating with an increase of the Fuhrman grade and tumour size while Notch3 and 4 receptors were directly correlated with tumour size." (PMID 26482227, 2015). "The Notch3 and Hes1 gene expression levels were significantly increased in the tumor tissue compared with the normal liver tissue from the same patient." (PMID 25668819, 2015). "For 71.8% of all the cases tested (n = 32), Notch3 mRNA levels in the tumor were higher than those in the normal liver tissue." (PMID 25668819, 2015). "There were a total of 9 studies that assessed the correlation between Notch3 expression and tumor clinicopathological parameters." (PMID 25996086, 2015). "In conclusion, our study demonstrated that Notch3 plays a role in modulating the stemness of tumor cells via the inactivation of the Wnt/β-catenin pathway." (PMID 25668819, 2015). "We confirmed that Notch3 gene expression was higher in tumor tissues compared with normal liver tissues in over 70% of all the HCC patients tested." (PMID 25668819, 2015). "We determined the Notch3 and β-catenin protein content in the tumor specimens and found Notch3 protein accumulation in the tumor tissues; this accumulation was inversely associated with the level of β-catenin." (PMID 25668819, 2015). "Tumor specimens from HCC patients were collected to measure Notch pathway-related genes with Q-RT-PCR assays, which indicated that the levels of Notch3, a Notch receptor family subtype, were increased in tumor tissues." (PMID 25668819, 2015). "The normalized data were plotted against Notch3 expression levels measured in the same tumor samples." (PMID 25356737, 2014). "The role of Notch3, one of four Notch receptors, is ambiguous: during brain development 17,27,28 and in some tumours 29–31 Notch3 appears to promote cell proliferation and gliogenesis similar to Notch1 32,33, the representative Notch receptor." (PMID 25164209, 2014). "The result indicated that ovarian HGSC tissues and primary tumor cell cultures with higher Notch3 expression levels tended to have lower expression levels of WWP2, and vice versa." (PMID 25356737, 2014). "While Notch3 appears to play a role in OvCa cell proliferation, tumor growth, and metastasis, additional investigations have implicated Notch signaling in chemoresistance." (PMID 25072022, 2014). "We found that miR-206 significantly suppressed tumor growth and metastasis at least in part by targeting the Notch3 signaling pathway in vitro." (PMID 24919811, 2014).
tumor (continued). "Notch3, Jagged1, Delta1 and the downstream effector gene, hairy and enhancer of split 1 (Hes1), are highly expressed in the HepG2 tumor cell line, which was thought to be necessary for malignant liver cell proliferation." (PMID 24919811, 2014). "Because p21 and pGSK3βSer9 contribute to Sorafenib resistance in vitro and since p21 levels and pGSK3βSer9 are down-regulated and up-regulated respectively in Notch3 KD cells, we examined their expression in tumor xenografts after sorafenib treatment." (PMID 24113128, 2013). "It remains to be seen if the effects of NOTCH3 inhibition can be attributed to the specific suppression of cancer stem cells within the tumor population." (PMID 23528888, 2013). "Overexpression of NICD1 or RBP-Jκ results in the transformation of normal breast epithelial cells, whereas Notch3 has been shown to play an important tumour suppressive role through its ability to upregulate p21cip1/WAF1 and induce senescence." (PMID 23863842, 2013). "Our experiments showed that the treatment with sorafenib (60 mg/kg/d) for 21 days inhibited tumour growth significantly more in both Huh7 (p=0.04) and HepG2 (p=0.01) Notch3 depleted xenografts than in GL2 xenografts." (PMID 24113128, 2013). "Notch3 expression in the cancer tissue was weaker than that of the corresponding non-tumor tissue in the SCLC group; the difference was statistically significant (P<0.01)." (PMID 23420695, 2013). "Altough γ-secretase inhibitors are today evaluated as promising inhibitors of Notch signaling in neoplastic disease, targeting Notch3 should be preferred for HCC therapy to avoid additional damage to non neoplastic cirrhotic liver." (PMID 24113128, 2013). "We also show for the first time that activity of Notch3 in particular, through its target gene, HEY-1, is associated with an aggressive tumour phenotype and an adverse prognosis." (PMID 23226563, 2012). "miR-206 increases apoptosis and inhibits tumor formation in cancer cells by directly targeting Notch3." (PMID 23071643, 2012). "Nevertheless, a positive auto-regulatory loop supports co-expression of Notch and its ligand is likely to amplify or sustain Notch3 signaling activation, thus providing a long-term survival advantage for tumor cells." (PMID 20953350, 2010). "Additionally, cancer cells can also induce NOTCH3 expression in neighboring CAFs through cell‐to‐cell contact, boosting angiogenesis and tumor growth." (PMID 39928309, 2025). "However, it was demonstrated that Notch3 has a pro-apoptotic role in regulating tumor angiogenesis independently of the Notch canonical pathway." (PMID 40429321, 2025). "Indeed, NOTCH3 knockdown decreased urothelial cancer cell proliferation in vitro and decreased xenograft tumour growth in vivo." (PMID 41008920, 2025). "Although the main function of NOTCH3 is to regulate angiogenesis, dysregulation of NOTCH3 activity may play an important role in tumorigenesis and tumor maintenance." (PMID 41018180, 2025). "Furthermore, AKT-dependent NOTCH3 activation was shown to drive tumor progression in a mouse model of stroma-rich CRC." (PMID 41034989, 2025). "Thus, Notch3 is the sole Notch receptor that is upregulated during tumor initiation and progression from Lfng-expressing centroacinar cells, suggesting an essential role for Lfng-dependent Notch3 signaling in this type of tumor." (PMID 39548190, 2025). "Upregulation of NOTCH2 expression may promote tumor cell migration and invasion, while high expression of NOTCH3 may be positively correlated with tumor cell proliferation and volume." (PMID 39925808, 2025). "Interestingly, we observed a dual role of serotonin and HTR2B stimulation under different conditions, and we found shared features of HTR2B + cells with tumor cells expressing NOTCH3." (PMID 41034989, 2025). "We found that NOTCH3 expression was highly elevated in tumor tissues, liver CSCs, and spheres." (PMID 40270470, 2025).
tumor (continued). "Moreover, they showed in a xenograft model that depletion of NOTCH3 significantly reduced tumour volume and weight and tumour metastasis." (PMID 41008920, 2025). "Increased NOTCH3 protein acetylation levels by suberoylanilide hydroxamic acid (SAHA), a histone deacetylase (HDAC) inhibitor, decreases NOTCH3 protein expression resulting in reduced tumour growth and enhanced sensitisation of urothelial cancer cells to cisplatinum." (PMID 41008920, 2025). "Notch3 is also found to be upregulated in CRC, compared to healthy tissue, and is associated with tumor recurrence and higher expression of Notch3 is associated with increased tumor growth rate." (PMID 41294868, 2025). "Given the previous observation of reduced E2 levels in the mouse model, we hypothesized that restoring estrogen signaling would attenuate depression-mediated tumor progression by targeting NOTCH3 driven pathways." (PMID 40940884, 2025). "Consequently, using Notch3 mutant mice, it was shown that tumor progression and angiogenesis are augmented when Notch3 is silenced." (PMID 40429321, 2025). "Actually, as a prognostic biomarker, NOTCH3 may contribute to tumor progression via participating in immune infiltration process in human cancer." (PMID 40796704, 2025). "Moreover, NOTCH3 expression level was significantly negatively correlated with the abundance of tumor immune cells, calculated using the ESTIMATE algorithm." (PMID 40940884, 2025). "Moreover, exogenous estradiol supplementation inhibited tumor growth and markedly reduced NOTCH3 expression in tumor tissues." (PMID 40940884, 2025). "IHC staining showed elevated NOTCH3 protein expression in CUS-exposed tumor tissues (p = 0.0027)." (PMID 40940884, 2025). "Among those, the Notch signaling pathway was found to be upregulated in preneoplastic lesions as well as in invasive tumors of the pancreas in both mice and humans, and targeting Notch2/Notch3 inhibited patient-derived xenograft tumor growth and decreased frequency of tumor-initiating cells." (PMID 39548190, 2025). "Moreover, nuclear Notch3 and HEY-1 expression was shown to be significantly associated with reduced OS and DFS following tumor resection." (PMID 39062863, 2024). "Our findings suggest that NOTCH3 may act as a crucial regulator of tumor immune cell infiltration and can serve as a valuable prognostic biomarker in gastrointestinal cancers." (PMID 38906903, 2024). "However, the potential functions and mechanisms of NOTCH3 in tumorigenesis and tumor immunology are still unclear." (PMID 38906903, 2024). "Additionally, Transwell and wound healing assays demonstrated that targeting NOTCH3 inhibited the migration and invasion of tumor cells." (PMID 39557868, 2024). "There have been many reports in the literature that NOTCH3 signaling may play an important role in tumor development, invasion, maintenance, and chemotherapy resistance." (PMID 38906903, 2024). "Additionally, we explored the effects of NOTCH3 knockdown and overexpression on tumor metastasis using a lung metastasis model in nude mice." (PMID 39286249, 2024). "In this report, we assessed the expression level of NOTCH3 as it connected to the prognosis of various cancers according to the independent Oncomine and GEPIA databases, revealing clear differences between tumor and normal tissue expression of NOTCH3 in different cancers." (PMID 38906903, 2024). "Our findings suggest that targeted therapies regulating FGA and NOTCH3 expression could improve patient prognosis based on specific tumor types and survival conditions." (PMID 39130639, 2024). "For example, hsa_circ_0058124 enhances PTC tumor invasion via the NOTCH3/GATAD2A pathway." (PMID 39051062, 2024). "IGF2BP3 maintains NOTCH3 mRNA stability by inhibiting CCR4-NOT complex-mediated deadenylation (in an m6A dependent manner), thereby maintaining the activation of NOTCH3 signal and increasing the transcription of downstream genes related to stem cells, and ultimately promoting tumor metastasis." (PMID 39403369, 2024).